ACE (angiotensin I converting enzyme)
Diseases named in the same sentence as ACE in open-access papers (continued):
Sharing a sentence is not in itself a finding about the gene and the disease.
COVID-19 (continued). "It was demonstrated that the serum ACE activity in patients with COVID-19 increased gradually after treatment, with a significant difference from the baseline level (P < 0.001)." (PMID 33238910, 2020). "In summary, there is currently no scientific evidence establishing a clear link between ARBs, ACE inhibitors, or ibuprofen and the worsening of COVID-19." (PMID 32415494, 2020). "In summary, CoVex identifies the protein BDKRB1, which appears to play a role in SARS-CoV-2 host cell entry and can be targeted by several ACE inhibitors widely used in clinical trials to treat COVID-19." (PMID 32665542, 2020). "Out of 22 eligible articles that investigated candidate genes (2 as associated with COVID-19), the top-ranked genes in the number of studies were ACE2, CLEC4M (L-SIGN), MBL, MxA (n = 3), ACE, CD209, FCER2, OAS-1, TLR4, TNF-α (n = 2)." (PMID 32917282, 2020). "This, in turn, has enabled the development of ACE inhibitors for the treatment of cardiovascular disease and candidate therapies for the treatment of COVID-19." (PMID 33146371, 2020). "Accordingly, among RAS-antagonists, ACE-inhibitors (ACEi) or angiotensin-receptor blockers (ARBs) have been suspected to be risky in COVID-19 patients." (PMID 32899439, 2020). "The baseline serum ACE activity in patients with COVID-19 was significantly lower than that in normal controls, with the lowest level in the severe COVID-19 patients." (PMID 33238910, 2020). "The NCT04351581 is a randomized, single mask (outcome assessor), parallel assignment clinical trial that will randomize hospitalized patients with COVID-19 to continue or discontinue their treatment with the ACE inhibitor or ARB." (PMID 32850989, 2020). "Because, COVID-19 shows its effect through ACE-2 and adipose tissue is very rich and important tissue in terms of ACE-2." (PMID 32765938, 2020). "In agreement, severe patients were older and hypertensive, which further supports the role of serum ACE activity in the development of COVID-19." (PMID 33238910, 2020). "Several studies have confirmed that patients with COVID-19 had a higher baseline prevalence of cardiovascular conditions and diseases for which treatment with ARBs and ACE inhibitors is often used." (PMID 33322089, 2020). "In the first few months of COVID-19 spread, a controversial topic was the use of angiotensin receptor blocking drugs (ARB) and ACE inhibitors (ACEI) in patients with COVID-19." (PMID 33304284, 2020). "A recent report indicated that the use of ACE inhibitors and ARBs was more common among patients with COVID-19 than among controls because of their higher prevalence of cardiovascular disease rather than because of their use of these medications." (PMID 33229624, 2020). "The clinical course of the disease has been challenged by the interaction of three genetic polymorphisms, all affected by COVID-19: first is the CYP2D6 enzyme system, second is the HO-1 anti-inflammatory gene, and third the ACE and ACE-2 enzyme systems." (PMID 32708430, 2020). "Another class of drugs that have been used for the treatment of COVID-19 is ACE inhibitors, such as fosinopril sodium, which is being studied in two clinical trials as a means to block the virus receptor." (PMID 33260370, 2020). "COVID-19 uses ACE to enter type II pneumocytes or intestinal epithelial cells in order to induce ACE2 internalization and shedding, resulting in the occurrence and development of acute respiratory distress syndrome (ARDS)." (PMID 33082858, 2020). "A joint statement issued on 17 March 2020 found that no experimental or clinical evidence demonstrating beneficial or adverse outcomes in COVID-19 patients using ACE inhibitors or ARB was available and that urgent additional research is needed." (PMID 32369402, 2020). "Given that ACE2 serves as the key receptor mediating SARS-CoV-2 entry into host cells and reduced ACE activity may contribute to COVID-19 severity, understanding this relationship is crucial." (PMID 40733537, 2025).
COVID-19 (continued). "Furthermore, SNPs on ACE and ACE2 genes were associated with musculoskeletal injuries in athletes, and recently with infection and the severity of COVID-19 in the general population." (PMID 39997971, 2025). "It was theorized that ACE-1 inhibitors and ARBs could be harmful in COVID-19, as increased ACE-2 activity could increase viral entry into cells." (PMID 39997475, 2025). "For example, genetic variants in specific targets, such as ACE and ACE2 SNPs, may impair the performance and muscular endurance of athletes and affect their return-to-play performance after COVID-19, which may also negatively affect their mental health." (PMID 39997971, 2025). "Dysregulation between ACE and ACE2 activity may underlie the increased risk for patients with cardiovascular diseases of a severe course of COVID-19, as well as serve as the mechanism of some cardiovascular complications." (PMID 40573885, 2025). "Nevertheless, in CF patients, ACE polymorphisms and the downregulation of ACE2 expression may contribute to the variability in COVID-19 severity." (PMID 40733537, 2025). "Furthermore, we identified that bradykinin and substance P, both inactivated by the angiotensin-converting enzyme (ACE), are diminished in critically ill COVID-19 patients." (PMID 40529720, 2025). "Genetic polymorphisms like ACE rs4646994, ACE2 rs2285666 GG, TMPRSS2 rs12329760 CC and the presence of the C allele may serve as predictive models for the severity of COVID-19." (PMID 39194697, 2024). "For instance, it remains unclear whether certain treatments commonly used for cardiovascular diseases, such as ACE inhibitors or statins, are beneficial or harmful in the context of COVID-19." (PMID 39768431, 2024). "The current report demonstrates that ACE and ACE2 intronic polymorphisms may play a decisive role in disease prognosis and could be further considered as possible predictors of COVID-19 severity and prognosis." (PMID 39194697, 2024). "Another thing worth exploring was angiotensin-converting enzyme (ACE) 2 and long COVID-19 symptoms." (PMID 39469144, 2024). "Interestingly, in another study renin inhibitors had the same effect as ACE inhibitors (ACEIs) and angiotensin II type 1 receptor blockers (ARBs) in the treatment of COVID-19." (PMID 39444690, 2024). "ACE inhibitors may be used in treatment for certain COVID-19 aftereffects, albeit there is currently insufficient evidence of this." (PMID 39200115, 2024). "Additionally, medications, including ACE inhibitors, angiotensin receptor blockers, thiazolidinediones and ibuprofen, have been shown to increase the incidence of thrombosis in COVID-19 due to the upregulation of ACE2." (PMID 38638797, 2024). "Furthermore, studies have validated that ACE polymorphisms can affect ACE2 expression, leading to the CF phenotype and pulmonary inflammation associated with the development of COVID-19." (PMID 38694803, 2024). "In regards to COVID-19, ACE inhibitors could reduce SARS-CoV-2 cell entry by reducing the availability of binding sites and reducing internalization of ACE2." (PMID 39062478, 2024). "According to recent ecological studies on COVID-19, countries that have a significant intake of food rich in antioxidants or foods with anti-angiotensin-converting enzyme (ACE) activity, like raw or fermented cabbage, show a lower rate of COVID-19-related fatalities when compared to other countries." (PMID 38347959, 2024). "The D allele has been linked with increased activity of the ACE enzyme, which we observed in the post-COVID-19 group but not in the COVID-19 group." (PMID 37108839, 2023). "In low- and middle-income countries (LMICs), inexpensive generic drugs like statins, ACE inhibitors, and ARBs, especially if used in combination, might be the only practical way to save the lives of patients with severe COVID-19." (PMID 36983871, 2023).
COVID-19 (continued). "We thought that risk factors related to COVID-19 severity (i.e., age, sex, and co-morbidities) acted as confounders; however, the statistical analyses showed that the serum ACE activity was not related to any of these variables." (PMID 37108839, 2023). "Likewise, others have shown that serum ACE activity was lower in patients with COVID-19 vs. controls." (PMID 37175942, 2023). "In this situation, pharmacological inhibition of the ACE/Ang II axis could have worsened the defect in the classical RAS observed during COVID-19." (PMID 37986086, 2023). "Based on prior database analyses, the frequency of the ACE II genotype within a population showed a remarkably negative association with mortality caused by SARS-CoV-2 infection, which indicated a favorable influence of the ACE II genotype on COVID-19 morbidity and outcome." (PMID 38058963, 2023). "The interrelationship between the ANPEP and ACE genes might impede the progression of COVID-19 from the initiation phase to the propagating phase in pediatric patients." (PMID 38813031, 2023). "The mechanism underlying the association between ACE I/D polymorphism and COVID-19 severity was not explored here." (PMID 38058963, 2023). "For COVID-19, similar findings have been published for ACE inhibitor and ARB withdrawal." (PMID 36983871, 2023). "ACE and ACE2 are essential parts of the renin-angiotensin system (RAS), which maintains blood pressure and electrolyte balance and has been implicated in the pathogenesis of ARDS in COVID-19 patients." (PMID 37762258, 2023). "The COVID-19 patients with different ACE gene allelic variants showed that age and D-dimer were not different between all variants' subgroups." (PMID 36644496, 2023). "Research shows the correlation between angiotensin-converting enzyme (ACE) deletion and insertion (D/I) polymorphism and COVID-19 risk; yet, conclusive evidence is still lacking." (PMID 38058963, 2023). "Moreover, ACE-2 serum levels would have given us a better insight on predicting the severity and outcome of COVID-19." (PMID 37426824, 2023). "Moreover, continuation of ACE inhibitor/ARB outpatient treatment after hospitalization has beneficial effects on COVID-19 outcomes, whereas discontinuing treatment can be harmful." (PMID 36983871, 2023). "In an observational study including 1686 patients hospitalized for COVID-19, use of ACE inhibitors or angiotensin receptor blockers (ARBs) was associated with lower levels of inflammation and lower risk of the composite outcome of in-hospital death, mechanical ventilation, or dialysis." (PMID 36851722, 2023). "It has also been suggested that COVID-19 may be affected by the deletion/insertion (D/I) of an Alu repeat at the ACE locus (rs1799752, Intron 16)." (PMID 37328914, 2023). "Therefore, physiological profiles of ACE and ACE2 must be associated with the outcome of patients affected by COVID-19 by the impairment of angiotensin II to angiotensin 1–7 balance." (PMID 38032879, 2023). "Small observational studies in non-COVID-19 ARDS also report evidence of endogenous ACE-inhibition." (PMID 38103056, 2023). "Treatment of liver disease and metabolic syndrome with ACE inhibitors may promote increased susceptibility to SARS-CoV-2 and increased severity of COVID-19." (PMID 37243158, 2023). "Moreover, the expression of AT1R and ACE was also significantly increased in ACE2-positive brain cells of COVID-19 patients." (PMID 37239234, 2023). "Previous studies have reported the relevance of ACE activity in the severity of COVID-19." (PMID 37108839, 2023). "The upregulation of ACE and depletion of ACE2 could result in an imbalance in ACE/ACE2, such as increasing the ACE/ACE2 ratio to accelerate the disease progression of acid-induced ALI or COVID-19 ALI." (PMID 37763673, 2023).
COVID-19 (continued). "An increase in ACE-expressing EVs in COVID-19 patients with severe disease and a trend of increased TMPRSS2 may be indicative of the loss of ACE on the cell surface which leads to endothelial injury and facilitates inflammation." (PMID 36982991, 2023). "Since the beginning of the COVID-19 pandemic, the use of ACE inhibitors and ARBs in hypertensive patients with COVID-19 has been controversial due to the proven role of RAS in regulating blood pressure mechanisms and the role of ACE2 receptors as an entry gate to SARS-CoV-2." (PMID 37762258, 2023). "Nonetheless, in resource-poor countries inexpensive generic drugs like statins, ACE inhibitors, and ARBs might be the only practical way to save the lives of patients with severe COVID-19." (PMID 36983871, 2023). "Moreover, the literature-based pathway analysis uncovered a set of specific genes, such as CALCA, ACE, SIRT1, TNF, IL6, CCL2, and others, that were found to mediate the association between OA and COVID-19." (PMID 38020136, 2023). "The interplay between the ANPEP and ACE genes could potentially prevent the progression of COVID-19 from the initiation phase to the propagating phase in pediatric patients." (PMID 38813031, 2023). "Lastly, we assessed immune cell surface expression of the activation marker, ACE, which may be a contributing factor to COVID-19 outcomes and immunotherapeutic responses in patients requiring antihypertensive treatment (e.g., ACE inhibition)." (PMID 38259435, 2023). "The REMAP-CAP study tested the hypothesis that pharmacological inhibition of the classical ACE/Ang II RAS with an ACE inhibitor or an angiotensin receptor blocker (ARB) could improve the outcomes for severe COVID-19 patients." (PMID 37986086, 2023). "Moreover, the loss of NO-mediated vasodilation is further amplified by an angiotensin converting enzyme (ACE)/ACE2 imbalance in COVID-19 that favors angiotensin II-mediated vasoconstriction." (PMID 37108759, 2023). "Considering this, estrogens and ACE inhibitors could be a potential target for the tratment of other viral infections with a similar pathophysiology of COVID-19." (PMID 37746500, 2023). "According to animal studies, ACE inhibitors or ARBs may upregulate ACE2 gene expression in cardiac cells, which might increase COVID-19 susceptibility." (PMID 35387486, 2022). "A meta-analysis also concluded that ACE I/D polymorphism can be a beneficial marker for acute lung injury/ARDS prognosis and the genotypes may be used to treat acute lung injury/ARDS in COVID-19 patients." (PMID 36531237, 2022). "Several FX containing seaweeds might be able to reduce the degree of angiotensin-converting enzyme (ACE)/angiotensin II (AngII)/angiotensin receptor II type 1 (ATR1) axis dominance by inhibiting ACE in COVID-19 patients." (PMID 35983376, 2022). "Recent clinical studies of patients with COVID-19 have not identified a clear relationship between ACE inhibitor use or ARB use and disease risk or severity, and current guidelines support continuance of ACE inhibitors or ARB during infection." (PMID 35359831, 2022). "Association of ACE and ACE2 polymorphism with the outcome of COVID-19." (PMID 35250987, 2022). "Whether increased ACE2 expression in the lungs occurs in humans upon long-term ACE inhibitor therapy, and whether and how that might affect COVID-19 severity, remain the major open questions that our study aimed to stimulate." (PMID 35448480, 2022). "Mitogen-activated protein kinase 14 (MAPK14), angiotensin-converting enzyme (ACE), toll-like receptor (TLR4), and MAPK8 are the main players that are directly linked to the majority of the phytocompounds and played a major role in COVID-19-associated pathways." (PMID 36144690, 2022). "Prospective studies—in particular, randomized, placebo-controlled trials may provide clearer insight about the effect of ACE inhibitors or ARBs in patients with COVID-19." (PMID 34775787, 2022).
COVID-19 (continued). "In this regard, the ACE-DD genotype contributes to this scenario by being associated with enhanced circulating and tissue ACE1 concentration and activity and ACE I/D polymorphism with pulmonary embolism in COVID-19." (PMID 35685188, 2022). "ACE activation enhances the production of angiotensin II, which may have a role in COVID-19 and RA pathology." (PMID 35054471, 2022). "However, it is essential to take into account that BBB-crossing ARBs (e.g., telmisartan, candesartan) or ACE inhibitors (e.g., captopril, lisinopril, fosinopril, perindopril, ramipril, trandolapril) may show better results in neurologic, cognitive and memory impairments caused by COVID-19." (PMID 36187294, 2022). "Overall, the overexpression of ACE in COVID-19 patients may aggravate psoriasis favoring also cardiovascular complications, particularly in patients with severe psoriasis." (PMID 35566548, 2022). "Studies have shown that an imbalance in the interaction between ACE and ACE2 may be one of the chief mechanisms underlying COVID-19-related lung injury." (PMID 35836993, 2022). "Our original hypothesis that overshooting ACE activity as a result of the reduced counter-regulation by ACE2 may be a part of COVID-19 pathophysiology was confirmed." (PMID 35330406, 2022). "However, recent findings have shown that ACE inhibitors and the angiotensin type 1 receptor (AT1R) blockers do not increase the susceptibility to viral infection and the severity of COVID-19." (PMID 36352477, 2022). "In this study, we performed an ambispective case-control analysis to evaluate the association between non-genetic factors and genetic factors, including the polymorphisms rs4646994 (ACE), rs2285666 (ACE2), and rs11385942 (LZTFL1), and COVID-19 severity and long-term symptoms in Colombian population." (PMID 35795626, 2022). "In addition to the up-regulation of ACE2, another concern for the use of these drugs in patients with COVID-19 relates to the potential increase in levels of bradykinin, which is knows to be metabolized by ACE." (PMID 35566706, 2022). "In order to improve the understanding of how genetic variants of ACE and ACE2 are involved in the severity of COVID-19, we included a total of 481 individuals who showed clinical manifestations of COVID-19 and were diagnosed by reverse transcription PCR (RT-PCR)." (PMID 35250987, 2022). "Although we identified ACE2 as an important mediator of reduced intrinsic ACE activity in severe COVID-19, a significant portion of this reduction remained unaccounted for, and alternative pathways of angiotensin II degradation or endogenous ACE inhibition should be sought in subsequent studies." (PMID 36418458, 2022). "An altered ACE/ACE2 expression ratio could contribute to severe outcomes in COVID-19 patients, as it does for cardiovascular diseases." (PMID 35250987, 2022). "Although more common among the COVID-19 decedents with cardiac microthrombi, outpatient use of ACE inhibitor/ARB was not independently associated with cardiac microthrombi after multivariable adjustment." (PMID 34905515, 2022). "Based on the hypothesis that the RAAS can contribute to the genesis of the COVID-19-related cytokine storm, ACE inhibitors and sartans have been studied in patients with COVID-19, but their efficacy is still uncertain." (PMID 35208467, 2022). "A large observational study suggested that ACE-inhibitor (ACEI)/Angiotensin II receptor blocker (ARB) therapy at least did not increase susceptibility to COVID-19 or worsen the outcome of COVID-19 patients." (PMID 35681221, 2022). "Interestingly, Garvin and colleagues reported altered KKS in bronchoalveolar lavage fluid (BALF) of patients with COVID-19, showing reduced levels of ACE in combination with enhanced ACE2 and kininogen expression." (PMID 35812405, 2022). "In some studies, however, patients on ACE inhibitors and azithromycin were not at increased risk of poor outcomes from COVID-19." (PMID 35572676, 2022).